RNU7-94P (RNA, U7 small nuclear 94 pseudogene)
Gene: Small nuclear RNA gene on chromosome 12 (106,282,927 to 106,282,989, reverse strand). Ensembl gene ENSG00000238609.
Homologues: Orthologues: chimpanzee U7 (100% identical). Paralogues in human: RNU7-70P (86% identical), RNU7-37P (81% identical), RNU7-73P (81% identical), RNU7-82P (81% identical), RNU7-12P (79% identical), RNU7-13P (79% identical), RNU7-35P (79% identical), RNU7-7P (79% identical), RNU7-88P (79% identical), RNU7-113P (78% identical), RNU7-128P (78% identical), RNU7-14P (78% identical), and 141 more.